IL6 (interleukin 6)
Diseases named in the same sentence as IL6 in open-access papers (continued):
Sharing a sentence is not in itself a finding about the gene and the disease.
cognitive decline (continued). "Emerging evidence has shown that pro-inflammatory cytokines, such as interleukin (IL)-6 and IL-8, are particularly promising as serum biomarkers for PSCID, as their levels show a positive trend among those experiencing cognitive decline." (PMID 41542283, 2024). "Chronic neuroinflammation, marked by elevated pro-inflammatory cytokines such as IL-6 and TNF-α, plays a pivotal role in accelerating cognitive decline." (PMID 39767653, 2024). "Inhibition of NF‐κB can reduce the expression of pro‐inflammatory cytokines (such as IL‐6, IL‐1β, and TNF‐α) and increase the expression of BDNF, thereby ameliorating the cognitive decline of diabetic mice." (PMID 37864452, 2024). "IL‐6 is elevated in both the CSF and serum of people with AD47, 48 and higher peripheral levels in late midlife predict cognitive decline some 10 years later." (PMID 39030746, 2024). "-MaR1 improved cognitive decline by reducing pro-inflammatory cytokines (TNF-α, IL-6, MCP-1) and increasing anti-inflammatory cytokines (IL-2, IL-10) levels." (PMID 39452854, 2024). "Studies have shown that an increase in peripheral pro-inflammatory markers such as C-reactive protein (CRP), Interleukin-6 (IL-6) and soluble CD40 ligand (sCD40L) accompanies cognitive decline." (PMID 37686198, 2023). "Specifically, higher inflammation levels correspond to elevated levels of interleukin-6 (IL-6) and C-reactive protein (CRP), leading to an accelerated rate of cognitive decline." (PMID 38075216, 2023). "We found by RT-PCR an increase of the expression of mRNA for IL-1β and IL-6 as well as for IFN-γ, pointing to these cytokines, as targets for modulation in cognitive decline." (PMID 37187754, 2023). "These IL-10(-/-) mice also produce more pro-inflammatory cytokines IL-1β, IL-6 and TNF-α in the plasma, suggesting IL-10 inhibits cognitive decline via its propensity to mitigate inflammation." (PMID 35308288, 2022). "Changes in serum levels of IL-6, IL-1β, and TNF-α reflective of systemic inflammation and their correlation with cognitive decline during accelerated aging were similar to those of hippocampal NGPF2." (PMID 36479357, 2022). "Inflammatory cytokines, including IL-6, IL-10, CRP, MCP-1, ICAM-1, and TNF-α, play an important role in the development of poststroke cognitive decline." (PMID 35111122, 2021). "High levels of IL-1, IL-6, CRP, and TNF-α were also found to be potentially predictive markers for the development of Alzheimer's disease (AD) or cognitive decline." (PMID 32257550, 2020). "Second, some circulating pro-inflammatory markers such as IL-6 and CRP will likely increase in these subjects and result in global cognitive decline and hippocampal atrophy." (PMID 33363509, 2020). "Accumulating evidences suggest that interleukin-6 (IL-6), one of the main elevated proinflammatory cytokines in PND, plays a critical role in cognitive decline after surgery." (PMID 30804943, 2019). "In the control group, there were bivariate correlations between IL‐1β, IL‐6, and IL‐8 and lower MMSE scores and between IL‐13 and slower rate of cognitive decline (albeit at a significance level of P < 0.05 and notwithstanding correction for multiple testing)." (PMID 26999434, 2016). "In a study examining the relationship between inflammatory markers and baseline cognitive status, as well as subsequent cognitive decline, it was found that interleukins IL-8 and IL-12, rather than IL-6, are independent predictors of cognitive deterioration." (PMID 40305179, 2025). "Increased cytokine activity (IL-6, TNF-α, IFN-γ) and T-cell infiltration may affect brain function, leading to cognitive decline." (PMID 40124366, 2025). "In addition, cytokines including IL-10, IL-6, and TNF regulate synaptic pruning, elimination, and plasticity; their imbalance may therefore cause excessive synapse loss or impaired circuit refinement, ultimately leading to cognitive decline or visual dysfunction." (PMID 41226665, 2025).
cognitive decline (continued). "Nonetheless, in our study, diagnostic accuracy of α-klotho, IL-6, TNF-α, and BDNF is low, and there is no statistical difference between the cognitive decline and cognitive undiminished groups." (PMID 40950978, 2025). "Inflammatory markers, notably interleukin-6 (IL-6), were elevated in NAFLD patients and may contribute to the observed cognitive decline." (PMID 38542310, 2024). "Second, elevated RHR may also be a marker of autonomic dysfunction, which may drive the development of cognitive decline and dementia by activating inflammatory pathways and increasing the levels of inflammatory markers such as hs-CRP, IL-6, and fibrinogen." (PMID 39044526, 2024). "In KCa3.1−/− KO mice, surgery neither induced cognitive decline nor microglial proliferation although plasma IL-6 was increased (p < 0.001)." (PMID 36927341, 2023). "For example, some cross-sectional and longitudinal studies involving people without dementia found that higher levels of interleukin (IL)-6 and C-reactive protein (CRP) are associated with an increased risk for all causes of dementia and cognitive decline." (PMID 37168718, 2023). "We hypothesized that low-grade inflammation, estimated by interleukin-6 (IL-6), tumor necrosis factor alpha (TNF-α), and high-sensitivity CRP (hs-CRP), is a predictor of cognitive decline in the general population." (PMID 36195448, 2022). "A longitudinal study of cognitive decline in older adults used a panel of 8 blood-based markers, including APOE, plasma amyloid β 42/40 ratio, telomere length, serum glucose, cystatin C, C-reactive protein (CRP), interleukin-6 (IL-6), and albumin." (PMID 33946285, 2021). "Both IL‐6 and CRP have consistently been reported to be strongly correlated with various age‐related diseases and are considered valuable predictors of physical and cognitive decline." (PMID 33024560, 2020). "The extent of the elevation of proinflammatory cytokines (IL-1β, IL-6, TNF-α, etc.)in both the central nervous system and the systemic circulation after surgery may relate to the degree of cognitive decline." (PMID 32214903, 2020). "This is the first meta-analysis to investigate baseline IL-6 and longitudinal global cognitive decline in non-demented adults." (PMID 29358917, 2017). "Our results suggest that there is an association with high, but not intermediate, baseline concentrations of IL-6 and an increased likelihood of global cognitive decline upon follow-up." (PMID 29358917, 2017). "In the WHI cohort, higher DII scores were associated with elevated concentrations of inflammatory markers, including IL-6, TNF-α, and hs-CRP, which can cross the blood–brain barrier, induce neuroinflammation, and damage neurons and synaptic function, ultimately leading to cognitive decline." (PMID 41228485, 2025). "The literature has shown that chemotherapy directly results in an upregulation of various well-known pro-inflammatory mediators, such as IL-1β, TNF-α, MCP-1, IL-6, etc., which contribute to symptoms including but not limited to fatigue, peripheral neuropathy, and cognitive decline." (PMID 38731449, 2024). "In addition, recent meta-analyses found relationships between higher baseline IL-6 but not TNFα and steeper cognitive decline, with less published research on IL-1β levels and longitudinal cognitive change." (PMID 39055623, 2024). "Elevated IL-6 but not CRP in midlife prospectively predicts cognitive decline, evidenced by MMSE." (PMID 36334250, 2023). "A negative correlation was found between IL-6 levels and cognitive decline." (PMID 30186038, 2018). "However, not all studies confirm the link between IL-6 levels and cognitive decline." (PMID 40305179, 2025). "The second aim was to evaluate the mediating role of IL-6 in the longitudinal association between long-lasting T2DM and neurodegeneration-specific biomarkers in multiethnic community-dwelling middle-aged and older adults without previously diagnosed cognitive decline." (PMID 40606939, 2025).
cognitive decline (continued). "IL-6 has attracted considerable interest within the context of Parkinson’s disease (PD), a progressive neurodegenerative disorder characterized by motor manifestations such as tremors, rigidity, and bradykinesia, coupled with non-motor symptoms encompassing cognitive decline and mood disturbances." (PMID 39015561, 2024). "However, evidence that multiple serum and CSF proinflammatory cytokines and chemokines, including IL-2, IL-1β, IL-6, IL-10 and IFN-γ, decline over time and may be undetectable in AD suggests that related topic study outcomes can vary with disease stage and cognitive decline." (PMID 37760836, 2023). "After 11 years of follow-up, the 5 blood-based markers that correlated best with cognitive decline were APOE (present/absent), cystatin C, serum glucose, CRP, and IL-6." (PMID 33946285, 2021). "There are several other inflammatory markers that were not assessed; however, CRP, IL-6, sTNF-RII, and IL-1ra were chosen because previous studies have demonstrated these markers to be elevated and correlated with cognitive decline in BCS." (PMID 30126098, 2018).
ischemia (266 papers, 1997 to 2026). A hypoperfusion of the BLOOD through an organ or tissue caused by a PATHOLOGIC CONSTRICTION or obstruction of its BLOOD VESSELS, or an absence of BLOOD CIRCULATION. "AGO attenuates hepatic IRI by improving redox balance, modulating NO metabolism, and reducing IL-6-associated signaling and apoptosis, with stronger protection when administered before ischemia." (PMID 41977427, 2026). "Elevated CRP levels reflect activation of the IL-1/IL-6 axis and are strongly linked to plaque vulnerability, myocardial necrosis, and recurrent ischemia." (PMID 41226718, 2025). "In pathological conditions, increased pro-inflammatory cytokines such as IL-1β, IL6, and TNFα cause brain damage due to ischemia associated with BBB disruption." (PMID 39204239, 2024). "Activation of microglia and astrocytes caused by ischemia leads to production of pro-inflammatory cytokines (IL-6, IL-1β, and TNF-α), and the release of chemotactic factors, which further increase the permeability of BBB." (PMID 38364236, 2024). "Similar to clinical studies, we found that release of ischemia was associated with a substantial liberation of IL-6 into the effluent perfusate in all experiments." (PMID 36943408, 2023). "Conversely, TNF- α and IL-6 are associated with a tendency to develop ischemia or atherosclerotic events." (PMID 35684317, 2022). "Inflammatory cascade along with BBB is related to elevated levels of tumor necrosis TNF-α and IL-6, causing brain injury, peaked at 24 h after ischemia in the central nervous system (CNS)." (PMID 34454522, 2021). "The results of Evans blue staining showed similar cardiac risk areas after subsequent exposure to 30 min of ischemia and 24 h of reperfusion between the IL-6-treated and control mice." (PMID 33428604, 2021). "We showed that the neuroprotective effects of PGZ in the early post-ischemia phase were associated with an anti-inflammatory response involving a decrease in IL-6 and M1-type macrophages in male rats." (PMID 29110250, 2018). "IL-6 signaling has also been linked to plaque initiation and destabilization and to adverse outcomes in the setting of acute ischemia." (PMID 29312959, 2017). "CMD IL-6 levels were positively associated with episodes of ischemia/metabolic stress, as defined by a lactate:pyruvate ratio greater than 30 and glutamate levels greater than 80 μmol/L." (PMID 28740480, 2017). "Infarction, local and systemic inflammation, neutrophil infiltration, coagulation and ST elevation/resolution were compared between wild-type (WT) and IL-6-deficient (IL-6−/−) mice after 1 h ischemia and 0, 1⁄2, 3, and 24 h reperfusion." (PMID 26935770, 2016). "Left lung ischemia-reperfusion was associated with reduced levels of both IL1β (p < 0.001) and IL6 (p < 0.001) in the right lung." (PMID 24146959, 2013). "Proinflammatory cytokines, such as tissue necrosis factor-α (TNF-α), interleukin (IL)-1β, and IL-6 have been implicated as important mediators of ischemia/reperfusion injury following both focal and global cerebral ischemia." (PMID 23056034, 2012). "Transient focal ischemia caused 23 and 20 fold increases in IL-6 and Tnf-α mRNA respectively, suggesting that ischemia induces neuroinflammatory responses in the brain." (PMID 22348126, 2012). "Proinflammatory cytokines, such as tissue necrosis factor-α (TNF-α), interleukin (IL)-1, and IL-6, have been implicated as important mediators of ischemia/reperfusion injury following both focal and global cerebral ischemia." (PMID 23056034, 2012). "The present study showed that the effect of use of MK-886 (6 mg/kg) before induction of ischemia and at the onset of reperfusion caused significant lowering (P < 0.05) in serum levels of the IL-6 and TNF-α." (PMID 22196041, 2011). "An increase in IL-6 levels in neurons at risk of ischemia may be associated with neuroprotection; however, excessive production of IL-6 in the brain leads to neurodegenerative changes." (PMID 40305179, 2025).
ischemia (continued). "Increased levels of the pro-inflammatory factor IL-6 induced by ischemia often cause endothelial cells to express adhesion factors and chemokines, which in turn activate monocytes to release relevant inflammatory cytokines, leading to the formation of atherosclerotic thrombosis." (PMID 38895632, 2024). "In our animal study, the mRNA level of IL-6, TNFα, and IL-1β was increased 24 h after ischemia induction; this was associated with the presence of M1-like macrophages and the expansion of cerebral infarction although the mRNA level of IL-6 was low during the first 3 h." (PMID 29110250, 2018). "In particularly we aimed to find changes in arterial blood gas, electrolytes, plasma inflammatory protein IL-6, and plasma metabolites associated with hypothesized ischemia-reperfusion injury and the received regimen." (PMID 30469433, 2018). "Depending on the timeline of ischemia, a direct injection of IL-6 into the brain after ischemia can reduce ischemic brain damage." (PMID 40305179, 2025). "HSPA1A was shown to inhibit the production of proinflammatory factors (TNF-α and IL-6) and inhibit the activity of matrix metalloprotein kinases (MMPs) and iNOS in both in vitro and in vivo models of ischemia." (PMID 39924492, 2025). "Especially, the pro-inflammatory phenotype of microglia induced by ischemia and LPS is characterized by increasing productions of iNOS, IL-1β, IL-6, TNF-α, reactive oxygen species (ROS) and NO resulted in the dysfunction of the CNS." (PMID 40289983, 2025). "Exosomes derived from MSCs can ameliorate inflammation after acute ischemia or ischemia–reperfusion injury by modulating anti-inflammatory molecules (IL-4 and IL-10) and pro-inflammatory cytokines (IL-6, TNF-α, and IL-1β), and inhibiting microglia activation." (PMID 40771978, 2025). "The concentrations of Il‐6, Tnfα, Il‐16, Fcgr3α, and Nos2 were elevated following ischemia/reperfusion, which were partially mitigated by RF." (PMID 39915908, 2025). "In line with our previous study, we observed that renal epithelial cells expressed low levels of NF-Kβ, TNF-α, and IL-6 when cyclic hind limb ischemia was performed during bilateral ischemia (BIR + RIPerC group)." (PMID 41239227, 2025). "Microglia, the primary mediators of neuroinflammatory processes in the CNS, respond to various pathological changes, including injury, ischemia, and infection, by expressing a range of cytokines like IL-1β, IL-6 and TNFα." (PMID 38600587, 2024). "Nesfatin-1 reduced microglia proinflammatory activation by decreasing IL-1β, IL-6, and TNFα expression in a rat ischemia model." (PMID 39295865, 2024). "CRP, an acute-phase inflammatory marker synthesized primarily by the liver under conditions such as infection, trauma, and ischemia, increases in response to proinflammatory cytokines, particularly interleukin-6." (PMID 39685802, 2024). "Previous research has shown Melittin’s anti-inflammatory actions in cases of cerebral ischemia, where it reduced the elevated cytokine levels (IL-1β, IL-6, TNF-α) post-ischemia by inhibiting the NF-κB signaling pathway linked to inflammatory factor production." (PMID 38732255, 2024). "As the iris is a metabolically active tissue, pro-inflammatory cytokines (interleukin-6, prostaglandin E2, and tumor necrosis factor-alpha) are released following surgical injury, trauma, or ischemia." (PMID 38983009, 2023). "Applying tourniquets during TKA has been shown to increase the levels of the inflammatory factors CRP and IL-6, probably as a result of ischemia and damage to soft tissue." (PMID 37119309, 2023). "Before visualization, synonyms (e.g., salvia miltiorrhiza and danshen), different spellings (e.g., ischemia, ischemic, and ischaemic), abbreviations (eg, IL-6 and interleukin-6), and singular/plural forms (e.g., arrhythmia and arrhythmias) should be merged." (PMID 37383699, 2023). "The ischemia-induced release of IL-6 was strongly attenuated in CD4-CD73–/– mice, suggesting adenosine-mediated modulation." (PMID 36943408, 2023).